CDH1 (cadherin 1)
Diseases named in the same sentence as CDH1 in open-access papers (continued):
Sharing a sentence is not in itself a finding about the gene and the disease.
tumor (continued). "Notably, the youngest affected individual in this pedigree presented with congenital absence of mandibular incisors and was found to harbor additional genetic mutations alongside the pathogenic CDH1 variant, which was associated with a highly aggressive tumor phenotype." (PMID 41378303, 2025). "However, in these 2 cases, somatic CDH1 variants were detected in tumor samples." (PMID 38652475, 2024). "Molecularly, the patterns of E-cadherin loss follow a classic Knudsen’s two-hit tumour suppressor hypothesis, involving CDH1 mutation (50–60% cases), gene methylation (21–77% of cases) and/or loss of heterozygosity in the region of 16q22.1 (or whole chromosomal arm)." (PMID 35053458, 2022). "However, the difference in E-cadherin protein expression could be explained in some tumours, due to a differential copy number loss of CDH1 in cases that were CDH1WT." (PMID 35053458, 2022). "Besides, CDH1, coding for the E-cadherin protein, was reported to be linked to GC susceptibility and tumor invasion, and preliminary studies indicated the potential clinical value to employ CDH1 haplotypes in metastatic GC to stratify patients that will benefit from Trastuzumab-based treatments." (PMID 33968127, 2021). "Furthermore, rare CDH1 variants were identified in tumor DNA of 6/99 (6%) ODs." (PMID 33929593, 2021). "Specifically, increased expression of EMT-TFs leads to transcriptional repression of CDH1, encoding for junction protein E-cadherin with a central role in the maintenance of the polarized epithelial monolayer and metastatic suppression during tumor progression." (PMID 35011635, 2021). "Since we previously observed a strong effect of holo-LCN-2 on tumour cell migration, we then performed qRT-PCR analysis of migration-associated genes, such as the transcription factor Snail, the epithelial marker CDH1, the mesenchymal marker fibronectin as well as the stemness markers CD24 and CD44." (PMID 31772326, 2020). "Surprisingly, despite the presence of a CDH1 mutation, E-cadherin expression could still be immunohistochemically detected in tumor tissue with a monoclonal antibody raised against E-cadherin (Agilent Dako FLEX Monoclonal Mouse Anti-Human E-Cadherin, Clone NCH-38)." (PMID 32362280, 2020). "The E-cadherin gene (CDH1, OMIM192090) on chromosome 16q is responsible for encoding the E-cadherin, which has been demonstrated to play a key role in cellular adhesion, cell motility, differentiation, growth, migration, and signaling as well as to function as a tumor suppressor of BC." (PMID 30975222, 2019). "Finally, diffuse GC is characterized by diffuse pattern of infiltration: the complete loss of adherence properties by the cancer cells generate the so called “signet ring cells” histology, which is often due to CDH1 (Cadherin 1) tumor suppressor loss at genetic level." (PMID 30205505, 2018). "Molecularly, the patterns of E-cadherin loss often follow Knudsen’s two hit hypothesis for a classic tumour suppressor gene, involving CDH1 mutation, gene methylation and/or loss of heterozygosity in the region of 16q22.1 (frequently involving the whole chromosomal arm)." (PMID 25849106, 2015). "These analyses identified several differentially methylated genes linked to invasiveness (e.g., PHYHD1, WNT4, STAT6, CDH1, CDH13), aggressive behaviour (e.g., AIP, PDCD1, LINE-1), and tumour regrowth (e.g., TERT, FAM90A1, ING2)." (PMID 41866138, 2026). "The resulting Lgr5+ hepatocyte-derived BrafV600E-driven tumours expressed the zone 1 marker CDH1 and had reduced expression of the zone 3 and WNT marker GLUL." (PMID 41261129, 2026). "CDH1 acts mainly in late mitosis and G1 phase and remains unchanged or reduced in human cancers as a tumor suppressor." (PMID 41374402, 2025). "The epithelial cell-cell adhesion molecule cadherin 1 (CDH1/E‐cadherin) forms the adherens junctions and plays a critical role in tumor development." (PMID 40688506, 2025).
tumor (continued). "Viruses such as HPV, EBV, HBV, and HCV can downregulate E-cadherin through overexpression of DNA methyltransferases (DNMTs), promoting aberrant methylation of the CDH1 gene and contributing to tumor progression." (PMID 40723356, 2025). "Subsequently, the overexpression of Cdh1 inhibited the protein expression of Tim4 in tumour‐conditioned RAW264.7 cells and eliminated the elevated expression of Tim4 caused by PCS." (PMID 40604335, 2025). "Consistently, we observed a higher frequency of deletions in CDH1, which encodes E-cadherin, a critical suppressor of tumor metastasis, and RUNX3, which promotes E-cadherin expression and inhibits EMT, in these patients." (PMID 41002582, 2025). "CDH1 expression was higher in C1, suggesting a role in maintaining cell-cell adhesion and epithelial-like characteristics, indicating better tumor differentiation." (PMID 40860670, 2025). "The mesenchymal markers SNAIL, SLUG, TWIST, and ZEB1 were upregulated in OX40+ tumor ECs, whereas the adhesion molecules CDH1 (encoding E-cadherin) and CDH5 (encoding VE-cadherin) were downregulated." (PMID 40026246, 2025). "In contrast, MYC, STAT3, CDH1, and CCND1 were significantly downregulated in tumor tissues compared to normal controls, suggesting a loss of tumor-suppressive or differentiation-related functions." (PMID 40766612, 2025). "Drugs such as histone deacetylase inhibitors (HDACi) and DNA methyltransferase inhibitors (DNMTi) are under investigation for their ability to restore tumor suppressor expression, including CDH1." (PMID 40757085, 2025). "Given the limited evidence that CDH1 PV carriers are more likely to develop neoplasia, it is essential to examine the incidence of preneoplastic lesions and the risk of developing invasive CRC in this population." (PMID 40323501, 2025). "Using Xenium data, the SKNY algorithm was applied to detect tumor spatial domains (yellow) and extract their boundaries (green) based on the expression levels of the epithelial cell marker CDH1." (PMID 39965034, 2025). "In the samples of mesenteric metastases with severe fibrosis, CDH1 stained more strongly at the periphery of the tumour nests, which were in contact with the stroma." (PMID 40998421, 2025). "This study demonstrates that CDH1, CDH2, and CDH3 are significantly upregulated in NSCLC and are associated with tumor progression, poor prognosis, and advanced disease stages." (PMID 40860670, 2025). "We further detected the expression of Cdh1 in tumour‐conditioned RAW264.7 cells, and PCS inhibited the protein expression of Cdh1." (PMID 40604335, 2025). "CCL26high OSCC had a characteristic of tumor invasive phenotype with upregulated CLDN8/20 and reduced keratin KRT36, which was significantly associated with EMT markers (CDH1, CDH2, VIM, SNAI2)." (PMID 39931245, 2025). "Integration of multi-omics data including genomics, transcriptomics, and epigenomics is likely to deepen our understanding of CDH1-related tumor biology and identify novel targets." (PMID 40757085, 2025). "Differential expression of key metastasis-associated genes (CDH1, JUNB, and DUSP5) confirmed the scaffold’s ability to recapitulate important molecular features of the tumor microenvironment." (PMID 40558895, 2025). "Looking at a specific gene, CDH1 is highly expressed in tumour, but many transcripts were also detected in connective tissue, whereas the COMET segmentation identified fewer cells compared to Xenium." (PMID 40735471, 2025).
tumor (continued). "Downregulation of CDH1 disrupts intercellular adhesion, promotes epithelial–mesenchymal transition in tumor cells, and enhances their invasive and metastatic capabilities." (PMID 40150405, 2025). "Taken together, these findings suggest that anti-PD-L1-CRT therapy dramatically alters expression of cytoskeletal genes, such as KRT5 and CDH1, in tumours, along with changes in cell morphology." (PMID 40670667, 2025). "MiR‐145 downregulation is linked to hypermethylation of CDH1, whose reduced expression promotes EMT, increasing tumor cell invasiveness." (PMID 40060195, 2025). "For instance, CDH1’s upregulation in our analysis contrasts with its canonical tumor-suppressive role, a paradox observed in other cancers." (PMID 40693059, 2025). "CDH1 showed strong, diffuse membranous expression and weak cytoplasmic staining in primary tumour cells." (PMID 40998421, 2025). "An interesting finding in the SH canine UC cell line showed the highest CDH1 expression after curcumin treatment, and the SH cell line is from a xenograft model of a lymph node metastasis, representing an aggressive tumor." (PMID 40509054, 2025). "SNAI1 is an EMT regulator that promotes tumour invasiveness by repressing CDH1/E-cadherin transcription." (PMID 40642068, 2025). "Previous work demonstrated the tumor-suppressor function of the CDH1 gene, and TP63 has been proposed as genomic target of the oncogene miR-301b, which promotes cell invasiveness in PC through the downregulation of CDH1." (PMID 39791744, 2025). "This newly identified CDH1–CTNNB1–ESR1–GRPR–YAP1 axis defines a female-specific tumour metastasis route, providing some potential therapeutic targets." (PMID 40500450, 2025). "This supports the functional evidence that CDH1 inactivation promotes aggressive tumor behavior and contributes to worse clinical outcomes." (PMID 40757085, 2025). "GC patients with CDH1 deficiency typically present with DGC with a high risk of PM, a “cold” tumour microenvironment, and a poor prognosis." (PMID 40299206, 2025). "Studies have shown the weak radiologic-pathologic correlation on the identification and tumor size of ILC, especially in ILCs with a CDH1 truncating mutation or null/focal expression of E-cadherin." (PMID 39941785, 2025). "Hypermethylated gene promoters can serve as blood-based DNA methylation biomarkers signaling occult metastatic disease or recurrence (for example, CDH1 or RARB methylation in circulating tumor DNA)." (PMID 41301491, 2025). "CDH1 is a vital gene associated with EMT, and various studies have demonstrated the close relationship between EMT and the tumor immune microenvironment in different cancers." (PMID 41404730, 2025). "On the other hand, Hp induces DNA methylation in two ways: directly, through the effect of its pathogenic product CagA protein, and indirectly, via chronic inflammation and the CpG-island methylation of tumor-suppressor genes such as CDH1, p16, and IL1β." (PMID 38542354, 2024). "Tumour tissues from patients 1, 3, and 4 showed high CDH1 expression, whereas those from patients 2 and 5 showed decreased CDH1 expression." (PMID 38594611, 2024). "The decrease in the invasion and migration ability of tumor cells is often accompanied by increased expression of the core molecule CDH1, decreased expression of CDH2, and decreased expression of VIM." (PMID 38397980, 2024). "In P/LP germline CDH1 carriers, an inactivating CDH1 mechanism (second hit) was identified in 4 of 6 explored matched tumor samples (66.7%)." (PMID 38652475, 2024). "CDH1 expression was significantly lower in PROM2+ than in PROM2‐ tumours (p = .002) whereas other markers including VIM had an increased expression (p = .002)." (PMID 38515278, 2024).
tumor (continued). "Among them, upregulated genes such as CAMK2N1, IGFBP4, RGS2, WNT5A, and CDH1 have both tumor suppressor and inhibitory effects on EMT." (PMID 39768220, 2024). "CDH1 is a member of the cadherins superfamily, which are calcium-dependent adhesion molecules that partake in cell recognition, tissue morphogenesis and tumor suppression." (PMID 38429796, 2024). "SNAIL suppresses the expression of E-cadherin by binding to the e-boxes in the CDH1 promoter and recruiting the multisubunit repressor complex, a crucial process in tumor cells." (PMID 38605400, 2024). "A statistically significant decrease in the level of CDH1 (p = 0.005) was established in peritoneal metastases that suggested partial EMT during the transition from primary tumor cells to metastatic cells." (PMID 39519394, 2024). "Further, we compared the effects of each pUMAP cluster on genes associated with critical HT29 tumor biomarkers: KRAS, BRAF, CDH1, CYNNB1, and MET." (PMID 39605490, 2024). "The cell adhesion protein CDH-1 localized on the cell surface is involved in tissue organization and can thus prevent tumor invasion and metastasis." (PMID 39123454, 2024). "ARHGAP35, as a tumor suppressor, induces CDH1 expression and cooperates with E-cadherin to activate LATS kinase and inhibit tumor cell growth." (PMID 38263362, 2024). "Since loss of CDH1 is a key determinant of ILC, it strongly suggests that the original tumor was of lobular histology." (PMID 38198519, 2024). "In PDAC, cooperation with cadherin-3 prevents CDH-1 from negatively affecting tumor growth and positively enhances tumor aggressiveness and invasiveness." (PMID 39123454, 2024). "An inactivating CDH1 mechanism (second hit) was identified in 4 of 6 explored matched tumor samples (66.7%) in P/LP germline carriers." (PMID 38652475, 2024). "Again, the methylation profiles of the RASSF1, CDH1, PAX1, and PTEN phosphatase and tensin homolog (PTEN) tumor suppressor genes were analyzed, and higher plasma values of methylation were found for CDH1 and PAX1 genes in malignant ovarian lesions." (PMID 38275400, 2024). "CDH1 (E-cadherin gene), situated on chromosome 16q22.1, is a cell-to-cell adhesion molecule and tumor-suppressor protein." (PMID 39274207, 2024). "While CDH1 loss is characteristic of ILC and correlates with an initial low tumor grade, the mutation also serves as a significant long-term contributor to metastasis and poor long-term survival rates despite often being diagnosed in early stages of disease." (PMID 39594781, 2024). "Consistently, exposure to Eo33-EV also induced up-regulation of Cdh1 and down-regulation of Cdh2 in tumor cells." (PMID 39061080, 2024). "Regarding the expression of transcription factor genes, the expression was higher in EPCAM-positive CTCs (CDH1, ZEB1, ZEB2) and in EPCAM-positive primary tumor cells (CDH1, SNAIL1, SNAIL2, ZEB2) compared to EPCAM-negative CTCs and tumor cells." (PMID 39456890, 2024). "The vast majority of close to 300 reported that CDH1 mutations are associated with HDGC and less commonly with other tumor susceptibility." (PMID 39596675, 2024). "The CDH1 gene, known to act as a tumor suppressor, plays an essential role in maintaining cell–cell adhesion, ensuring the orderly arrangement and stratification of epithelial cells." (PMID 39728992, 2024).
tumor (continued). "Co-culture of mouse tumor cells with Eo33, compared to Eo5, induced more substantial up-regulation of the epithelial marker E-Cadherin/Cdh1 and down-modulation of the mesenchymal molecule N-Cadherin/Cdh2." (PMID 39061080, 2024). "This case provokes questions regarding tumor genetics and molecular profiling of SDC in patients with germline CDH1 pathogenic variants." (PMID 38651154, 2024). "The role of downregulation for CDH1 has been frequently described in the literature as an effective method for tumor control." (PMID 38707537, 2024). "The GEPIA2 analysis results indicate that the top 5 key genes (Bcam, Cdh1, Ifrd1, Mxd1, and Timp1) based on the trajectory analysis of tumor cells can affect the survival of tumor patients." (PMID 38539232, 2024). "Consistent with the data on tumor tissues, CDH1 mRNA expression in most carcinoma cell lines derived from commonly occurring carcinomas was in the range of moderate to high." (PMID 37189027, 2023). "In this study, we analyzed multiple large transcriptomics, proteomics, and immunohistochemistry datasets on clinical cancer samples and cancer cell lines to determine the levels of CDH1 mRNA and E-cad protein in different carcinomas during tumor progression." (PMID 37189027, 2023). "Gene expression was evaluated in treated and untreated tumor cells; it was observed that the treatments with EC (300 μM) induced higher expression of the anti-proliferative genes Cdh1, Mtss1, Pten, Bmrs, Fat1, Smad4, and Nrf2." (PMID 37687058, 2023). "HCV core protein can reduce E-cadherin expression levels due to CDH1 gene promoter hypermethylation, with consequent dissociation of the β-catenin/E-cadherin complex, and stimulates tumor cell growth by GSK-3β inactivation and Wnt3a release." (PMID 37512809, 2023). "Reduced CDH1 expression or function in tumor tissues increases the likelihood of distant metastasis." (PMID 37608794, 2023). "The authors also observed an upregulation of metalloproteinases (MMPs) 1, 3, 9 and 13, relaxin receptors 1 and 2 (RXR1 and RXR2) and a downregulation of CDH1 (E-cadherin) compared to the original tumor." (PMID 37368765, 2023). "This leads to the re-expression of methylation-silenced tumor-suppressor genes, such as fragile histidine triad protein (FHIT), CDKN2A, cadherin-13 (CDH13), cadherin-1 (CDH1) and Ras Association Domain Family Member (RASSF1A) both in vitro and in vivo." (PMID 37047090, 2023). "Although down-regulation of the CDH1 gene coding for E-cadherin enhanced the invasive capacity of tumour cells, their metastatic potential was diminished as the result of activated TGFβ signalling, decreased cell proliferation, and reduced stress resistance." (PMID 37259089, 2023). "The largest study was from Portugal which quantified the different second hit mechanisms in CDH1 in neoplastic lesions from 17 HDGC patients among 15 families comprising of 16 primary tumours and 12 metastases." (PMID 36869400, 2023). "Mesenchymal to epithelial conversion in vivo reinitiates proliferation, potentially mediated by heterotypic adherence junctions between newly re-expressed tumor-cell E-cadherin (CDH1) and osteoblast N-cadherin (CDH2)." (PMID 37296983, 2023). "In spite of CDH1 being absent in cancer cells, studies have indicated that restoring E‐cadherin expression can suppress tumor progression and invasion." (PMID 37901797, 2023). "The high purity of the fibroblast and tumor cell populations was confirmed by selective expression of cell type-specific genes including CDH1, EPCAM, and KRT8 for tumor cells and VIM, DCN, THY1, and COL3A1 for fibroblasts." (PMID 36868311, 2023).